SPOCK1 (SPARC (osteonectin), cwcv and kazal like domains proteoglycan 1)
Diseases named in the same sentence as SPOCK1 in open-access papers (continued):
Sharing a sentence is not in itself a finding about the gene and the disease.
pancreatic cancer (7 papers, 2017 to 2023). "By defining the expression pattern and functional properties of SPOCK1 in pancreatic cancer, we have identified a stromal mediator of extracellular matrix remodeling that indirectly affects the aggressive behavior of PDAC cells." (PMID 28486750, 2017). "First, we assessed SPOCK1 expression across microarray datasets that include normal pancreas samples and pancreatic cancer tissue." (PMID 28486750, 2017). "Overexpression of SPOCK1 in vitro and in vivo mediates chemoresistance by inducing the EMT phenotype; however, APG treatment dramatically blocked pancreatic cancer cell chemoresistance, migration, metastasis, tumor growth, proliferation, invasion, and cell survival." (PMID 34948250, 2021).
glioblastoma (6 papers, 2015 to 2023). The most malignant astrocytic tumor (WHO grade IV). "In glioblastoma cells, SPOCK1 expression is positively correlated with the mRNA and protein levels of vimentin and N-cadherin as shown by gain or loss expression of SPOCK1, while SPOCK1 can induce temozolomide resistance." (PMID 36358747, 2022). "SPOCK1 is upregulated in gastric, colorectal, lung, pancreatic, breast, esophageal squamous cell, and prostate cancer, as well as in glioblastoma, and it is associated with poor prognosis and EMT." (PMID 36358747, 2022). "Similarly, in glioblastoma, aberrant expression of SPOCK1 was shown to induce Temozolomide resistance." (PMID 38087364, 2023).
glioma (6 papers, 2007 to 2023). A benign or malignant brain and spinal cord tumor that arises from glial cells (astrocytes, oligodendrocytes, ependymal cells). "For example, studies have shown that SPOCK1 promotes cancer metastasis in glioma cells through the PI3K/AKT and Wnt/β-catenin signaling pathways." (PMID 38087364, 2023). "For example, SPOCK1 has already been reported to promote glioma cell proliferation, migration, and invasion." (PMID 30518750, 2018). "Some genes already described as related to glioma's invasion capacity by microarray studies such as SPOCK1, BCL2L2, EEF1A2 and TMEFF1 also appeared in the 50 first best triples." (PMID 17519038, 2007). "Furthermore, ChIP assay indicated that NR2C2 bound to SPOCK1 promoter and up-regulated SPOCK1 expression, thereby promoting malignant behaviors of glioma cells." (PMID 30518750, 2018). "PLOD2, Spp1, SPOCK1 and CRLF1 can also serve as new targets for anti-tumor microenvironment therapy of glioma." (PMID 36819132, 2023). "Western blot assay was used to determine the expression levels of NR2C2, SPOCK1, and NR2C2-uORF in glioma tissues and cells." (PMID 30518750, 2018). "We found that SPOCK1 was involved in NR2C2-induced regulation in glioma cells, whereas overexpression of NR2C2 increased the expression of SPOCK1." (PMID 30518750, 2018). "In a study of glioma, it was found that SPOCK1 and SPOCK3 could inhibit MT1-MMP-mediated MMP2 activation and inhibit glioma cell invasion by binding to MT1-MMP." (PMID 31338255, 2019).
lymph node metastasis (4 papers, 2015 to 2023). "A clinicopathological association study of the 64 GBCs found that SPOCK1 was significantly associated with histological differentiation (P = 0.012) and lymph node metastasis (P < 0.001)." (PMID 25623055, 2015). "We have demonstrated that the expression of SPOCK1 is associated with histological differentiation, lymph node metastasis, and the OS time of GBC patients." (PMID 25623055, 2015). "Moreover, immunohistochemistry showed that overexpression of SPOCK1 was significantly associated with histological differentiation, lymph node metastasis, and a shorter OS time of GBC patients." (PMID 25623055, 2015). "Even with no statistical significance for a correlation between SPOCK1 expression and the N value and M value, a larger number of cases with high SPOCK1 expression were observed in those with lymph node metastasis and distal metastasis." (PMID 31284511, 2019). "Furthermore, SPOCK1 also exhibited higher expression levels in invasive histological subtypes and patients with lymph node metastasis." (PMID 38087364, 2023). "Compared with patients without lymph node metastasis, those who developed metastasis exhibited significantly higher staining scores for SPOCK1 (P < 0.001), which suggested that SPOCK1 might function importantly in metastasis." (PMID 28940639, 2018).
liver cancer (3 papers, 2022 to 2023). An epithelial or non-epithelial malignant neoplasm that arises from the liver. "SPOCK1 is also implicated in the development and progression of liver cancer." (PMID 35186754, 2022). "In contrast, in human liver cancer, syndecan-1 expression decreases, or even disappears, whereas the cytoplasm is filled with SPOCK1." (PMID 35186754, 2022).
lung adenocarcinoma (3 papers, 2022 to 2026). A carcinoma that arises from the lung and is characterized by the presence of malignant glandular epithelial cells. "Among them, upregulated expression of SPOCK1 was observed in lung adenocarcinoma tissues and was associated with poor prognosis." (PMID 38087364, 2023). "The knockdown of SPOCK1 suppressed invasion and metastasis capabilities of lung adenocarcinoma cells, and the high expression of SPOCK1 was associated with low infiltration of CD8+ T cells." (PMID 38087364, 2023). "Our study reveals that SPOCK1 is a poor prognostic marker for lung adenocarcinoma and correlates with invasive metastasis of tumor cells, immunosuppressive tumor microenvironment formation, and low infiltration of CD8+ T cells in the tumor region." (PMID 38087364, 2023). "Our study showed that lung adenocarcinoma cells with high expression of SPOCK1 exhibited sensitivity to VER-15500." (PMID 38087364, 2023). "In our study, we found that knockdown of SPOCK1 effectively inhibits invasion and migration of lung adenocarcinoma cells and significantly suppresses the epithelial-mesenchymal transition process in tumor cells." (PMID 38087364, 2023). "In vitro experiments were conducted to knockdown SPOCK1 in lung adenocarcinoma cell lines A549 and H1975." (PMID 38087364, 2023). "Overall, these findings highlight the key role of SPOCK1 in promoting the malignant invasive characteristics of lung adenocarcinoma cells." (PMID 38087364, 2023). "Our study also revealed a close relationship between SPOCK1 and in vitro cell migration/invasion, as well as immune microenvironment remodeling in lung adenocarcinoma." (PMID 38087364, 2023). "Similar results were validated in cell lines, where lung adenocarcinoma cell lines showed higher expression of SPOCK1 than the normal lung epithelial cell line BEAS-2B." (PMID 38087364, 2023). "Both the wound healing assay and the transwell assay (including migration and invasion assays) demonstrated that knockdown of SPOCK1 significantly inhibited the migration and invasion abilities of lung adenocarcinoma cells." (PMID 38087364, 2023). "Additionally, we observed that SPOCK1 is mainly enriched in the invasive subtype of an early-stage lung adenocarcinoma cohort containing invasive subtype information." (PMID 38087364, 2023). "Therefore, SPOCK1 may serve as a novel therapeutic target and potential immunotherapy and prognostic biomarker for lung adenocarcinoma." (PMID 38087364, 2023). "It is suggested that SPOCK1 may be a potential therapeutic target for clinical lung adenocarcinoma." (PMID 38087364, 2023).
non-small cell lung carcinoma (3 papers, 2020 to 2025). A group of at least three distinct histological types of lung cancer, including non-small cell squamous cell carcinoma, adenocarcinoma, and large cell carcinoma. "In the case of non-small cell lung cancer, the presence of SPOCK1 contributes to the resistance of the third-generation tyrosine kinase inhibitor." (PMID 35186754, 2022).
ovarian carcinoma (3 papers, 2017 to 2023). A malignant neoplasm originating from the surface ovarian epithelium. "In ovarian cancer, the Protein Atlas Database clearly revealed that high SPOCK1 expression is a factor associated with poor prognosis and reduced survival rate." (PMID 37046698, 2023). "According to the Human Protein Atlas, SPOCK1 is a prognostic marker for ovarian cancer because its high expression is associated with significantly shorter survival." (PMID 37046698, 2023). "There are an increasing number of published studies discussing the oncogenic role of SPOCK1 in a variety of malignancies; however, studies exploring its implications in ovarian cancer, especially using human material, are still scarce." (PMID 37046698, 2023). "The significantly increased incorporation of BrdU provoked by SPOCK1 overexpression reflects the stimulated DNA synthesis (thus proliferation) in both ovarian cancer cell lines." (PMID 37046698, 2023). "Given the similar pattern observed in ovarian carcinomas, it is possible that SPOCK1 resides in the mitochondria." (PMID 37046698, 2023). "In line with this, ovarian cancer tissues and blood samples exhibited higher SPOCK1 levels than healthy controls." (PMID 37046698, 2023). "We therefore collected blood samples from patients with ovarian cancer and measured the SPOCK1 level by ELISA." (PMID 37046698, 2023). "SPOCK1 expression in human ovarian cancer tissues and in blood samples were studied by immunostaining and ELISA." (PMID 37046698, 2023). "Information can be extracted from comprehensive studies (mostly in silico), although, so far, only one publication has investigated the influence of SPOCK1 specifically in ovarian cancer." (PMID 37046698, 2023). "Human FFPE biopsies were utilized to evaluate SPOCK1 protein levels and localization in tumors and normal ovaries, and blood samples were collected to determine serum levels of the proteoglycan in ovarian cancer patients." (PMID 37046698, 2023). "Moreover, SPOCK1 levels were higher in untreated ovarian cancer serum and tissue samples and lower in recipients of chemotherapy." (PMID 37046698, 2023). "Although numerous publications have reported that SPOCK1 promotes the proliferation and migration of cell lines derived from different types of tumors, only one study has demonstrated that silencing SPOCK1 attenuated proliferation, migration and invasion of ovarian cancer cell lines." (PMID 37046698, 2023). "Here, we report for the first time that SPOCK1 is detectable in the blood samples of patients suffering from ovarian cancer, and that its level may correlate with chemotherapy treatment." (PMID 37046698, 2023). "In ovarian cancer, SPOCK1-201 and SPOCK1-001 mainly occur, as well as small amounts of SPOCK1-003." (PMID 37046698, 2023). "As a next step, we tested whether SPOCK1 exerts any effect on the migration of ovarian cancer cell lines." (PMID 37046698, 2023). "The purpose of this study was to explore the role of SPOCK1 in ovarian cancer." (PMID 37046698, 2023). "Our results indicate that SPOCK1 may serve as a therapeutic target and could be utilized for monitoring ovarian cancer." (PMID 37046698, 2023). "In addition, overexpression of SPOCK1 in ovarian cancer cells has also been shown to significantly promote the migration level of tumor cells." (PMID 38087364, 2023). "Furthermore, SPOCK1 levels in untreated ovarian cancer serum and tissue samples were higher than in chemotherapy-treated patients." (PMID 37046698, 2023). "Ovarian cancer patients had increased SPOCK1 serum levels compared to healthy controls." (PMID 37046698, 2023). "However, information on SPOCK1′s significance in ovarian cancer is limited." (PMID 37046698, 2023). "Therefore, we aimed to examine SPOCK1′s role in ovarian cancer in further detail." (PMID 37046698, 2023). "We do not yet know whether there is a direct functional link between SPOCK1 and CHD1L expression in ovarian cancer, and thus more research is required to elucidate the issue." (PMID 37046698, 2023).
urothelial carcinoma (3 papers, 2017 to 2020). A malignant neoplasm derived from the transitional epithelium of the urinary tract (urinary bladder, ureter, urethra, or renal pelvis). "Our findings were similar to the results in urothelial carcinoma (UC), in which higher SPOCK1 expression was correlated with unfavorable clinicopathological parameters and conferred a poor prognosis in UC." (PMID 33293473, 2020). "It is well known that an elevated expression of SPOCK1 is accompanied by a tendency toward an advanced T value and lymphatic invasion in urothelial carcinoma." (PMID 31284511, 2019). "In addition to the brain and liver, the higher expression of SPOCK1 in urothelial carcinoma correlates with a higher pathological tumor value, lymph node metastasis, higher histological grade, and more vascular and perineurial invasion." (PMID 31284511, 2019).
clear cell renal cell carcinoma (2 papers, 2023). "Sparc/osteonectin, cwcv, and kazal-like domains proteoglycan 1 (SPOCK1) has been reported to play an oncogenic role in certain cancer types; however, the role of SPOCK1 in the progression of clear cell renal cell carcinoma (ccRCC) remains elusive." (PMID 36766694, 2023).
head and neck squamous cell carcinoma (2 papers, 2020 to 2021). A squamous cell carcinoma that arises from any of the following anatomic sites: lip and oral cavity, nasal cavity, paranasal sinuses, pharynx, larynx, and salivary glands. "miR-150-3p could function as a tumor-suppressor in both head and neck squamous cell carcinoma and the overexpression of miR-150-3p bound to SPOCK1 to alleviate the aggressiveness of head and neck squamous cell carcinoma." (PMID 33958701, 2021).
microcephaly (2 papers, 2015 to 2017). A congenital or acquired developmental disorder in which the circumference of the head is smaller than normal for the person's age and sex. "Missense mutation in SPOCK1 encoding testican-1 causes intellectual disability with dyspraxia, dysarthria, partial agenesis of corpus callosum, and prenatal-onset microcephaly." (PMID 25852466, 2015). "The identified de-novo mutation of SPOCK1 might be protein-damaging which could potentially lead to developmental delay and microcephaly." (PMID 28155865, 2017).
Obesity (2 papers, 2022 to 2024). Accumulation of substantial excess body fat. "According to this report, SPOCK1 regulates adipogenesis-related genes, participates in thermoregulation, induces adipocyte differentiation, and is likely to be involved in the development of obesity and type 2 diabetes." (PMID 35186754, 2022).
Overgrowth (2 papers, 2020 to 2023). Excessive postnatal growth which may comprise increased weight, increased length, and/or increased head circumference. "Therefore, SPOCK1 is a novel therapeutic target for gingival overgrowth and its expression is a potential risk of EMT induction in cancerous lesions." (PMID 32555336, 2020). "We previously reported that Spock1-Tg mice exhibit gingival overgrowth in the absence of periodontal inflammation due to the promotion of epithelial-to-mesenchymal transition by SPOCK-1 overexpression." (PMID 38156070, 2023).
Sepsis (2 papers, 2022 to 2023). Sepsis is defined as life-threatening organ dysfunction caused by a dysregulated host response to infection. "Only one publication has so far reported the presence of SPOCK1 in serum samples from patients with sepsis." (PMID 37046698, 2023). "SPOCK1 has been detected in the blood circulation of patients with sepsis." (PMID 37046698, 2023).
Stroke (2 papers, 2025). Sudden impairment of blood flow to a part of the brain due to occlusion or rupture of an artery to the brain. "Likewise, while our analysis identified SPOCK1 and BCAN as ECM-related markers, other studies found ECM proteins like fibulin-1, fibronectin, and MMP9 elevated in stroke, highlighting consistent engagement of tissue remodeling pathways across stroke types." (PMID 41152969, 2025).
adenoma (1 paper, 2023). A neoplasm arising from the epithelium. "F ROC analysis for SPOCK1 predicting aberrant methylation in adenoma." (PMID 37779184, 2023).
asthma (1 paper, 2021). "The GM13-up related to interleukin-26 (IL26, PIK3R5, and LRRC2) was much higher expressed in severe individuals while the GM12-down module related to the nervous system (10%, p = 1.77E-04, i.e., TUBB2B, SPOCK1, and ASCL1) was much lower expressed in severe asthma individuals." (PMID 34759961, 2021).
astrocytoma (1 paper, 2025). "For example, COL20A1 and SPOCK1 were elevated in TCs for grade II and 3 astrocytoma samples respectively." (PMID 41366031, 2025).
breast tumors (1 paper, 2025). "Additionally, we compared SPOCK1 expression levels among normal tissues, primary breast tumors, and bone metastatic samples." (PMID 40837013, 2025).
cervical cancer (1 paper, 2025). A primary or metastatic malignant neoplasm involving the cervix. "SPOCK1 was investigated in ovarian serous cystadenocarcinoma (OV), cervical cancer (CESC), and endometrial cancer (UCEC) utilizing different databases." (PMID 40001977, 2025).
cervical squamous cell carcinoma (1 paper, 2025). A squamous cell carcinoma arising from the cervical epithelium. "The aim of this study was to explore the role of SPOCK1 in ovarian serous cystadenocarcinoma (OV), cervical squamous cell carcinoma and endocervical adenocarcinoma (CESC), and uterine corpus endometrial carcinomas (UCEC)." (PMID 40001977, 2025).
Cholecystitis (1 paper, 2015). The presence of inflammatory changes in the gallbladder. "Furthermore, protein expression levels of SPOCK1 were measured in 64 samples of archived paraffin-embedded GBC tissues and 60 cholecystitis gallbladder epithelial tissues by immunohistochemistry." (PMID 25623055, 2015).
cholelithiasis (1 paper, 2015). The presence of crystallized deposits forming in the gallbladder or biliary tree, primarily composed of cholesterol, bilirubin, and bile. "SPOCK1 expression was significantly higher in tumor tissues compared with that in cholelithiasis tissues (P = 0.002)." (PMID 25623055, 2015).
colon adenocarcinoma (1 paper, 2022). "We then found increased expression of SPOCK1 but not SPOCK2 was associated with poor overall survival (OS) in human colon adenocarcinoma (COAD)." (PMID 35046388, 2022).
colorectal adenoma (1 paper, 2023). An adenoma that arises from the colon or rectum. "Our results showed that all the genes of ZNF471, SND1, SPOCK1, FBLIM1, and OTX1 methylation with the area under receiver operating curve (ROC) more than 0.90 were significantly high in the colorectal adenoma and CRC compared with the normal group." (PMID 37779184, 2023). "Based on the results of the methylation chip of Illumina Infinium 450K detection and bioinformatic analysis, five hypermethylated genes, ZNF471, SND1, SPOCK1, FBLIM1, and OTX1, were selected for further investigation in the colorectal adenoma, CRC, and control normal tissues in our study." (PMID 37779184, 2023).
corticobasal syndrome (1 paper, 2019). Corticobasal syndrome (CBS) is a rare neurodegenerative disease characterized by multifaceted motor system dysfunctions and cognitive defects such as asymmetric rigidity, bradykinesia, limb apraxia, and visuospatial dysfunction. "Disease-specific analyses revealed lower group levels of FGF-5, FGF-19 and SPOCK1 in multiple system atrophy compared with progressive supranuclear palsy and corticobasal syndrome." (PMID 30867224, 2019).
fibrosis (1 paper, 2023). the formation of excess fibrous connective tissue in an organ or tissue in a reparative or reactive process. "Gingival fibrosis was enhnced by experimental periodontitis in both WT and Spock1-Tg mice without CsA administration." (PMID 38156070, 2023).